CRP (C-reactive protein)
Diseases named in the same sentence as CRP in open-access papers (continued):
Sharing a sentence is not in itself a finding about the gene and the disease.
Sepsis (continued). "In this study, we aimed to evaluate the ability of MR-proADM levels to predict 28-day mortality in sepsis patients, compared to other standard biomarkers (procalcitonin (PCT), C-reactive protein (CRP), and lactate), in three different levels of disease severity as measured by the SOFA score." (PMID 28185230, 2017). "Current targeting conventional markers (C-reactive protein, white blood cell, tumour necrosis factor-α, interleukins, etc.)are non-specific for diagnosing sepsis." (PMID 28794881, 2017). "For the oldest old patients, hs-CRP is not inferior to PCT in the diagnosis of sepsis and septic shock." (PMID 28764651, 2017). "It was also demonstrated that CRP failed to reflect sepsis severity, a previously published finding." (PMID 28380034, 2017). "CRP and PCT levels were shown not to be specific enough to assess the in-hospital mortality risk among pediatric sepsis patients." (PMID 28514310, 2017). "Due to the lack of specific clinical signs, numerous investigators have evaluated the usefulness of various markers of infection in diagnosing sepsis, including circulating complete blood count (CBC), C-reactive protein (CRP), procalcitonin (PCT), and numerous other tests." (PMID 28182674, 2017). "The serum PCT level rises rapidly than CRP levels and peaks within very short time; moreover, if the patient responds appropriately to the treatment, the level of PCT returns to normal range faster than CRP which makes it a better biomarker for sepsis." (PMID 28794881, 2017). "The initial blood investigations [total leucocyte count, absolute neutrophil count, C-Reactive protein (CRP)] were not suggestive of any sepsis therefore antibiotics were not started." (PMID 28061799, 2017). "The ongoing systemic activation of inflammatory biomarkers such as CRP, interleukin-6 and PCT during sepsis and septic shock may be an explanation of their correlation with PTX-3 levels in affected patients." (PMID 28793880, 2017). "In contrast, CRP, PCT and IL-6 are available in most of the hospital laboratories, and their combination in an easily computable score could improve the accuracy of sepsis diagnosis." (PMID 27287669, 2016). "Demographic and clinical patient information were recorded on admission to the ICU with blood samples taken for C-reactive protein (CRP), procalcitonin (PCT), interleukin-6, white blood cell count, as well as body temperature, age and the sepsis-related organ failure (SOFA) score." (PMID 27287669, 2016). "Other biomarkers that may assist in the diagnosis of sepsis includes serum procalcitonin (PCT) and C-reactive protein (CRP)." (PMID 27003588, 2016). "The present study shows a combined PCT, CRP and SOFA score, used to calculate a patient bioscore, may be a valuable predictive tool to accurately diagnose sepsis." (PMID 27287669, 2016). "CRP, PCT and IL-6 are used widely in attempting to clinically diagnose sepsis." (PMID 27287669, 2016). "Concentrations of TWEAK (but not GITRL) were further decreased in patients with sepsis and correlated with routinely used markers of inflammation and bacterial infection such as C-reactive protein, procalcitonin and Interleukin-6." (PMID 27124414, 2016). "In patient 4, unusually severe, progressive multiorgan failure developed after CVC-related sepsis, but normal liver function results and clotting and adequate CRP response did not support MAS." (PMID 27648582, 2016). "The two most commonly used markers in infection/sepsis diagnostics are PCT and CRP." (PMID 27597981, 2016). "However, the slightly elevated CRP and PCT values in sepsis survivors indicate a chronic low-level inflammatory status." (PMID 27056672, 2016). "Several bloodstream biomarkers in sepsis have been previously investigated, including PCT and CRP." (PMID 27287669, 2016). "Plasma C-reactive protein, interleukin-6, and interleukin-8 concentrations are higher in sepsis patients with neutropenia than in those without." (PMID 27077648, 2016).
Sepsis (continued). "Therefore, other parameters, such as CRP and PCT, are measured in addition to blood cultures when sepsis is suspected." (PMID 26761003, 2016). "The results of this study show that when threshold values of CRP, PCT and SOFA were taken into consideration by calculation of a bioscore value, this could be considered a statistically significant predictor for sepsis diagnosis." (PMID 27287669, 2016). "Then, multivariate analysis by logistic regression using the presence or absence of sepsis as a dependent variable and the parameters identified by univariate analysis found statistical significance of age, gender, CRP, PCT and SOFA." (PMID 27287669, 2016). "It was possibly due to CRP only being measured once at admission, the lack of series follow-up during sepsis, or the development of NeOAF." (PMID 27855722, 2016). "Two of the babies died of presumed sepsis at 4 and 6 days of age, respectively; both had raised C reactive protein with clinical signs of sepsis but negative cultures." (PMID 27382636, 2016). "However, plasma concentrations of ET, CRP, LAC, and PCT were significantly higher in septic shock than in sepsis (p < 0.05)." (PMID 26880865, 2016). "Biomarkers of infection and sepsis, such as procalcitonin (PCT) and C-reactive protein (CRP), could be used for the diagnosis and management of respiratory tract infections." (PMID 26927074, 2016). "In addition to CRP and PCT, the proinflammatory cytokine IL-6 is often measured in the context of sepsis." (PMID 26761003, 2016). "In the non-surgically treated patients (n = 140), CRP, PCT and SOFA score had significant diagnostic value in diagnosing sepsis." (PMID 27287669, 2016). "This small scale patient study could show that common sepsis markers PCT, CRP, IL6 and TNFα had low predictive value for early diagnosis of SIRS after cardiovascular surgery." (PMID 26263001, 2015). "Besides the mentioned acute phase proteins (cytokines, CRP, PCT) other plasma proteins are currently under investigation for their potential to indicate sepsis or inflammatory states." (PMID 26263001, 2015). "Although initial low CRP level was significantly with less severity of illness and better outcome, some critically ill neonates had CRP not significantly elevated at onset of sepsis." (PMID 26259626, 2015). "In a previous study of sepsis, endocan was not correlated to CRP and PCT, which is compatible with the present results." (PMID 25894539, 2015). "Patients with underlying gastrointestinal pathology, renal disorders, cholestasis, and pulmonary hypertension had a non-significant elevated CRP level at the onset of sepsis." (PMID 26259626, 2015). "The median CRP at presentation in the infants with NEO-KISS sepsis was 19.7 (IQR: 8.35–84.6) and 11.05 (IQR: 3–43.2) in the non NEO-KISS septic infants (p = 0.16)." (PMID 26305781, 2015). "Plasma CRP level should not be used to rule out severe culture-proven sepsis or guide the empirical choice of antibiotics." (PMID 26259626, 2015). "Elevated C-reactive protein (CRP) level is widely used in clinical practice as a marker to distinguish between neonates with or without sepsis." (PMID 26259626, 2015). "In recent ICU based studies, high PSP levels predicted mortality in septic adults, whereas established infection markers such as CRP or PCT were increased in presence of infections, but did not allow to stratify for sepsis mortality risk." (PMID 26588901, 2015). "Widely used infection biomarkers, such as CRP or PCT, have been investigated for their usefulness for distinguishing sepsis from other inflammatory diseases, assessing severity of illness, monitoring effectiveness of treatment, and predicting outcome in many previous studies." (PMID 25894539, 2015). "CRP is a sensitive marker for non-specific inflammation in the body, and therefore is also a highly correlated index of sepsis." (PMID 25780458, 2015).
Sepsis (continued). "Performances of each single marker (leukocytes, thrombocytes, C5, HP, SPHK1, and the routinely used laboratory parameters CRP and PCT) were compared with respect to various outcomes (sepsis, nosocomial infections, mortality) and time points of assessment (day 0, day 1, all days)." (PMID 26607226, 2015). "Unlike the levels of band cells, neither WBC numbers, nor platelet counts nor CRP concentrations differentiated patients with sepsis from patients with N-I SIRS." (PMID 25887201, 2015). "In our study CRP was found positive in 46.5% of culture negative cases, while it was negative in 23.7% of culture proven sepsis." (PMID 26150837, 2015). "Higher sensitivity was obtained when CRP was used to diagnose gram negative septicaemia than in the diagnosis of gram positive septicaemia (75% vs. 50%) with the same specificity." (PMID 25280754, 2014). "Still, those studies also found that CRP levels were higher in patients with mild organ dysfunction and sepsis, but CRP levels did not increase significantly with progression toward more severe stages of disease." (PMID 25407928, 2014). "Both prospective studies and retrospective studies have reported no predictive power of CRP for sepsis in trauma patients." (PMID 27602370, 2014). "SAA has so far not been investigated in sepsis and associations between SAA, CRP and albumin have not been assessed in canine pyometra." (PMID 25430894, 2014). "In place where blood culture is limited neonates having clinical features of neonatal sepsis with positive qualitative CRP assay and increased WBC should urgently be initiated on appropriate sepsis management in order to reduce morbidity and mortality associated with neonatal sepsis." (PMID 25280754, 2014). "ROC-analysis for the performances of inflammatory cytokine levels and CRP to rule out the possibility of sepsis and intracranial infection." (PMID 24887408, 2014). "Elevations of both CRP and PCT were added to the updated definition of sepsis in 2003." (PMID 24800240, 2014). "In patients with infection, CRP levels differed depending on whether the infection was localized, septic, or severely septic, whereas PCT levels were higher in patients with severe sepsis or septic shock." (PMID 25407928, 2014). "Higher sensitivity of 75% was observed when CRP was used to diagnose gram negative septicaemia compared to 50% that was observed in the diagnosis of gram positive septicaemia." (PMID 25280754, 2014). "Though C-reactive protein (CRP) and procalcitonin are currently used as clinical indicators of inflammation and infection, several other biochemical markers have been investigated for their ability to detect sepsis in an early, reversible phase." (PMID 24778096, 2014). "The AUCs for IL-2, IL-6, and IL-10 to rule out the possibility of sepsis and intracranial infection were bigger than CRP." (PMID 24887408, 2014). "The performances of IL-2, IL-6 and IL-10 to rule out the possibility of sepsis and intracranial infection are comparable with the role of CRP." (PMID 24887408, 2014). "In this study when sub-analysis was done the sensitivity of CRP to diagnose gram negative neonatal septicaemia increased to 75% while for gram positive septicaemia dropped to 50%." (PMID 25280754, 2014). "PCT was more reliable than CRP in diagnosing severe sepsis without shock, but it was not useful for diagnosing septic shock." (PMID 25960877, 2014). "Neonates with septicaemia due to gram negative bacteria were significantly found to have higher rates of positive CRP than neonates with gram positive septicaemia and with negative culture (p < 0.001, OR 8.2, 95 CI; 2.9-26)." (PMID 25280754, 2014). "Circulating suPAR levels, but not CRP levels, were reported to be higher on admission in nonsurvivor adults compared to patients who survived sepsis." (PMID 24882949, 2014).
Sepsis (continued). "More research will need to be done to see how this affects interpretation of CRP in Indian patients, though CRP will likely not be found to have the necessary discriminatory power for diagnosis and treatment of sepsis." (PMID 24772418, 2014). "CRP has been found to be significantly elevated in sepsis due to gram negative infections compared with gram positive infections suggesting a different immunomodulatory response." (PMID 24772418, 2014). "PCT has also been reported to be capable, more than CRP, of early discrimination between [severe] infection or sepsis on the one hand and non-infectious SIRS or uncomplicated infection on the other." (PMID 23762396, 2013). "Using ROC curve analysis to show performance in order to discriminate between SIRS and sepsis no overall significant difference was observed (p = 0.56) The CRP levels also correlated significantly with the SAPS2 score (rho 132, p = 0.0329)." (PMID 24039869, 2013). "A plasma HBP level >15 ng/ml was a better indicator of severe sepsis (with or without septic shock) than any other biomarker investigated (white blood cells, IL-6, procalcitonin and C-reactive protein)." (PMID 23883488, 2013). "The baby of case 1 was admitted to the neonatal unit with a raised level of C-reactive protein (CRP) and received ceftriaxone for suspected sepsis; nose and ear swabs obtained 2 days after delivery yielded GAS emm1, although blood and cerebrospinal fluid (CSF) cultures were negative." (PMID 23616448, 2013). "Póvoa and colleagues (2011) observed that the CRP levels were increased in severely immunosuppressed cancer patients with sepsis, and CRP course was alike from the presence or absence of neutropenia." (PMID 23874739, 2013). "The peak CRP level 70 mg/L ± 63 as a measure of acute phase response and inflammation showed a moderate but significant correlation with percentage CEACAM1 positive CD4+ T-cells in sepsis patients (R=0.553, P =0.031)." (PMID 23894299, 2013). "In the present study, both PTX3 and high PCT seemed to be independent predictors of severe sepsis while CRP did not." (PMID 23341967, 2013). "Nevertheless, in 32 critically ill patients with and without sepsis, we observed a significant correlation (r2 = 0.45, P < 0.001) between CRP concentrations at ICU admission and fibrinolysis assessed by the euglobulin lysis test." (PMID 24286072, 2013). "Our results suggest that, under a “classical” definition of sepsis, three typical biomarkers (CRP, PCT and DD) are not capable enough to differentiate septic from non-septic patients in the ER." (PMID 24050481, 2013). "FGF21 plasma levels measured at study entry correlated positively with the APACHE II score, but not with procalcitonin levels, nor with C-reactive protein, classical markers of sepsis." (PMID 23999826, 2013). "The present study makes a comparison between four biomarkers (sTREM-1, sCD163, PCT, and CRP) and one scoring system (SOFA scoring system), with the purpose of exploring which of these is/are more valuable in sepsis diagnosis, as well as in the prediction of its development and prognosis." (PMID 23935252, 2013). "Procalcitonin and CRP are biological markers currently in clinical use for detection of infection and unspecific inflammation, respectively, in the therapeutic management of SIRS and sepsis." (PMID 24039869, 2013). "However, the specificity and the value of CRP and PCT still have challenges; thus, there is a continuous need for searching for better biomarkers of sepsis." (PMID 23984377, 2013). "Persistently negative CRP values were rare in clinically probable non-CONS sepsis (1%), and do not occur more frequently in the presence of neutropenia." (PMID 24244325, 2013). "We developed of a computerized CRP-based sepsis evaluation protocol for VLBW infants that was generally well accepted by health care providers, but WBC results influenced antibiotic duration decision-making despite CRP results." (PMID 24244325, 2013).
Sepsis (continued). "Both PTX3 and PCT remained independent predictors for severe sepsis and case fatality also after adjustment for potential confounders whereas high CRP did not." (PMID 23341967, 2013). "Under a “classical” definition of sepsis three typical biomarkers (CRP, PCT and DD) are not capable enough to differentiate septic from non-septic patients in the ER." (PMID 24050481, 2013). "The time course of CRP as a marker of appropriate treatment, as has been suggested for PCT, and as a marker for the end of infection is of potential interest, although few studies have reported these aspects during sepsis." (PMID 24286072, 2013). "Our cohort was septic as evidenced by high markers of sepsis (PCT and CRP)." (PMID 24350088, 2013). "We showed a higher serum level of PCT, hs-CRP, and IL-6 in neonates with sepsis compared to those without sepsis." (PMID 22708043, 2012). "C-reactive protein (CRP), procalcitonin (PCT) and absolute neutrophil count (ANC) are biomarkers that may be used as adjunctive tests in the diagnosis of inflammation, sepsis and infection." (PMID 23272177, 2012). "This was higher than the CRP threshold value of 99 mg/L found in our study, but CRP concentrations of 80-100 mg/L have been used to differentiate sepsis from non-infectious SIRS in medical and surgical ICU patients." (PMID 23275327, 2012). "In this study, suPAR levels were correlated to CRP levels in the whole study population, but not in the group of patients with sepsis." (PMID 22221662, 2012). "The areas under the ROC curves for sCD163, CRP, and PCT for the diagnosis of sepsis were, respectively, 0.856(95%CI: 0.791–0.921), 0.696(95%CI: 0.595–0.797), and 0.629(95%CI: 0.495–0.763), At the recommended cut-off 1.49 ug/mL for sCD163, the sensitivity is 74.0% with 93.3% specificity." (PMID 22911680, 2012). "Among the conventional biomarkers of sepsis, an interleukin 6 concentration showed significant differences between survivors and non-survivors, while procalcitonin and C-reactive protein failed." (PMID 23088388, 2012). "We also found that sCD163 was superior to CRP and PCT for the differentiation of sepsis." (PMID 22911680, 2012). "On admission, neonates with sepsis had a higher WBC count, IL-6, PCT, and hs-CRP levels compared with those neonates without sepsis." (PMID 22708043, 2012). "A negative CRP, however can be useful in aiding the decision to discontinue antibiotics especially if the neonate has no clinical feature of sepsis." (PMID 22958461, 2012). "SOFA score is not as practical or as rapid a test as CRP to evaluate sepsis severity as it is calculated by adding platelet count, PaO2/FiO2 ratio, serum bilirubin, creatinine, and the Glasgow Coma Scale." (PMID 23171626, 2012). "Our study also found that sCD163 was superior to CRP and PCT levels and SOFA scores for the evaluation of sepsis severity and for the dynamic monitoring of sepsis, which may be attributed to the pathogenesis of severe sepsis." (PMID 22911680, 2012). "For diagnostic and prognostic purposes in critical care, PCT is an advance on C-reactive protein and other traditional markers of sepsis, but is not accurate enough for clinicians to dispense with clinical judgement." (PMID 22911680, 2012). "Of the 420 neonates with suspected sepsis, 196 (46.7%) had positive CRP while 224 (53.3%) had negative CRP." (PMID 22958461, 2012). "We aimed to assess whether in patients with severe sepsis requiring admission to ICU the initial and/or third day CRP values could be as good predictors of mortality as other well known complex predictors of mortality (i.e., SOFA scores, and APACHE II)." (PMID 23171626, 2012). "As postnatal CRP was only measured on infants who were clinically suspected of having sepsis, a significant proportion of neonates did not have CRP measured postnatally, precluding regression analysis of post-natal CRP data." (PMID 23272177, 2012).